AKT1 (AKT serine/threonine kinase 1)
Diseases named in the same sentence as AKT1 in open-access papers (continued):
Sharing a sentence is not in itself a finding about the gene and the disease.
breast cancer (continued). "For the role of Akt isoforms in cancer development, earlier studies revealed that systematic Akt1 deficiency inhibited primary cancer development, but promotes breast cancer migration and metastasis." (PMID 36180910, 2022). "6.3% (N=619) of breast cancer patients carry the AKT1 E17K mutation, associated with increased mortality." (PMID 35402264, 2022). "These associations remained similar after additionally adjusted for breast cancer stage, despite that a more advanced stage was associated with relative over-expression of AKT1 and RPS6KB2, compared to an earlier stage." (PMID 35608730, 2022). "AKT1 E17K is a hotspot mutation, the most frequent AKT1 mutation in breast cancer, and a highly recurrent AKT1 mutation in many other cancer types." (PMID 35402264, 2022). "This is also in line with what was observed in another clinical trial (NCT01277757), enrolling advanced breast cancer patients with PIK3CA/Akt1 or PTEN mutations or loss, where the AKT inhibitor, MK-2206, showed limited clinical activity." (PMID 35337095, 2022). "PIK3CA activation, PTEN loss mutations, and AKT1-E17K mutations are common in breast cancer, and mutations in these genes can cause AKT to be dysregulated." (PMID 35311116, 2022). "In previous clinical studies in Asia, TAS-117 has shown clinical efficacy in PIK3CA-mutated endometrial and ovarian cancers, in breast cancer cases harboring PIK3CA or AKT1 mutations, and in patients with ovarian clear cell carcinoma." (PMID 36039910, 2022). "Dysbindin domain-containing protein 2 variant DBNDD2:34 that was upregulated in BRCA1 mutated breast cancer was found downregulated in the AKT1 silenced sample compared to control (siNoN)." (PMID 35892586, 2022). "Inositol-tetrakisphosphate 1-kinase variant ITPK1:27 was found over expressed in breast cancer but was also found downregulated in the AKT1 silenced sample compared to control (siNoN)." (PMID 35892586, 2022). "The Akt1-E17K mutation existing in the PH domain has been observed frequently in breast carcinoma, ovarian carcinoma, and malignant meningioma with increased oncogenicity, particularly by facilitating AKT binding with PIP3, which promotes the action of AKT." (PMID 36539659, 2022). "AKT is central to the PI3K/AKT/phosphatase and tensin homolog (PTEN)/mTOR pathway, which is activated in almost 70% of breast cancers through mutations involving Akt1, PTEN, and PI3K." (PMID 34948307, 2021). "The frequency of AKT1 mutations in breast cancer was 7.4%, and they were found more frequently in human epidermal growth factor receptor 2 (HER2)-negative breast cancer subtypes, although this was not statistically significant (P = 0.08)." (PMID 34670536, 2021). "In conclusion, the rate of mutated AKT1 in breast cancer was 7.4%, and it correlated with the HER2-negative subtype." (PMID 34670536, 2021). "PTEN inactivation mutations occur in 9%, 7%, 2%, and 15% of HR+HER2-, HR+HER2+, HR-HER2+, and TNBC breast cancer, respectively, and Akt1 activation mutations occur in 7%, 2%, and 3% of HR+HER2-, HR+HER+, and TNBC breast cancer, respectively." (PMID 35578699, 2021). "Among them, a mutation in Akt1 in human breast cancer and gastric cancer has been found by researchers, and the mutation can stimulate this kinase by enhancing its membrane connection, thus directly correlating Akt1 with the occurrence of cancer." (PMID 34987399, 2021). "Twenty-eight patients initially had metastases, 148 of the 283 patients who initially had early breast cancer relapsed (137 and 11 with wild-type and AKT1 mutations, respectively), and 48 died of breast cancer." (PMID 34670536, 2021). "The reported frequency of AKT1 mutations in breast cancer is between 1.4 and 8.2%, and they are associated with histogenesis of hormone receptor positive subtype." (PMID 34670536, 2021). "The overall prevalence of Akt1 E17K mutation was 6.3% in breast cancers but it varied with tumor grade (11.1% in grade 1 and 1.9% in grade 3)." (PMID 34298660, 2021).
breast cancer (continued). "We observed that the mutations/deletion of NEDD4L was mutually exclusive with the activation of AKT signaling pathway (PTEN deletion/mutations, epidermal growth factor receptor (EGFR), PI3KC, or AKT1 mutations/amplification) in breast cancers." (PMID 34278744, 2021). "The TCGA (The Cancer Genome Atlas Program) data showed that in a predominantly Caucasian breast cancer cohort, AKT1 mutations had a frequency of 3% in most hormone receptor positive breast cancers." (PMID 34670536, 2021). "Similar to Akt1 inhibition, Akt3 deficiency also promotes breast cancer cells migration, invasion and metastasis due to upregulation of S100A4 and increased activation of HER2 and discoidin domain receptor tyrosine kinase 1/2." (PMID 34419139, 2021). "Breast cancers with AKT1 mutations were more likely to be ER-positive (P = 0.016), PR-positive (P = 0.002), and HER2-negative (P = 0.001)." (PMID 34093841, 2021). "Meanwhile, the most frequent mutation in the AKT1 gene (E17K substitution) is observed in approx. 4% of breast cancer patients." (PMID 33669698, 2021). "For breast cancer patients, AKT1 E17K mutation frequencies between 1.4% and 8.2% have been described in tissue." (PMID 34885114, 2021). "The reported frequencies of AKT1 mutations are between 1.4 and 8.2% in breast cancer and 2.2 and 4.1% in endometrial cancer." (PMID 34670536, 2021). "While knockdown of Akt1 in breast cancer cell lines caused an increase in cell migration and invasion, genetic ablation of Akt1 in mouse models of mammary tumor decreased tumor metastasis." (PMID 34298660, 2021). "AKT1 mutations are associated with HER2-negative subtype in breast cancer and in endometrial cancer with endometrioid histology." (PMID 34670536, 2021). "Here, the authors sequence breast cancers from Mexican-Hispanic patients and find that these patients have a higher percentage of Akt1 mutations compared to Caucasian and Asian populations, suggesting these are clinically actionable." (PMID 33854067, 2021). "PIK3CA and AKT1 gene mutations are common in breast cancer, and PIK3CA mutation is usually found in ER-positive and HER-2 positive breast cancer." (PMID 34552932, 2021). "Akt1 copy gain/high mRNA expression was associated with poor prognosis of basal-like 2 (BL2) breast cancer, a subgroup of TNBC." (PMID 34298660, 2021). "We were able to achieve reasonable specificity, although such thresholds will vary by technical factors, cancer type and molecular background (in our dataset, all breast cancer patients had AKT1 or PIK3CA mutations)." (PMID 34045463, 2021). "According to the COSMIC database, the frequency of AKT1 mutations is about 4% in breast cancer and 15% in meningiomas, and elevated expression is more common for endometrium (8.14%) and lung (8.73%) cancers." (PMID 33572326, 2021). "In our cohort, breast cancers with AKT1 mutations were significantly associated with positive ER- (P = 0.016) and PR (P = 0.002) but negative HER2- (P = 0.001) status." (PMID 34093841, 2021). "HER2 mutations were found least frequently in triple-negative breast cancer, while AKT1 mutations were found at a similar frequency in hormone receptor-positive HER2-negative breast cancer and triple-negative breast cancer." (PMID 32919527, 2020). "A study involving 313 Chinese breast cancer patients found that the mutation frequency of AKT1 in Chinese breast cancer patients was 3.2%, and it is considered a sensitive target for the treatment of breast cancer." (PMID 33062007, 2020). "We were able to show that reduced ARHGAP29 expression in breast cancer cells is associated with reduced AKT1 levels." (PMID 33291460, 2020). "The mutation frequency of AKT1 in Chinese breast cancer patients is 3.2%, and it is considered to be a sensitive target for the treatment of breast cancer." (PMID 33062007, 2020).
breast cancer (continued). "One of the major oncogenic pathways in breast cancer is PI3K/AKT/mTOR, which is frequently upregulated by activating mutations in PIK3CA, MAP3K1, and AKT1, or inactivating mutations in PTEN, leading to increased growth signaling." (PMID 32926574, 2020). "AKT1 mutations have been identified in 6–7% of oestrogen receptor-positive breast cancer metastases, and a more comprehensive biomarker analysis, including mutational status of all AKT isoforms, is underway on FAKTION samples." (PMID 32035020, 2020). "Zhang and coworkers, studying another large cohort of Chinese breast cancer patients, confirmed a high frequency of AKT1 mutations (8%) in these patients, all pertaining to the HR+HER2- subgroup." (PMID 32210163, 2020). "For example, in a mouse breast cancer model induced by polyoma middle T (PyMT) or ErbB2/Neu, loss of Akt1 significantly delayed tumor induction while loss of Akt2 accelerated this endpoint." (PMID 33110146, 2020). "A combination of three SNPs, including AKT1 rs2494740, AKT1 rs2494744, and AKT1 rs2498789, was found to significantly increase breast cancer risk in the context of high BMI and moderate and high alcohol intake (≥1 drink/day)." (PMID 31505792, 2019). "Activating mutations of the AKT1 gene have been described in various solid tumors, including breast cancer." (PMID 31835495, 2019). "Somatic mutations occurring in oncogenes PIK3CA and AKT1 have been widely reported in breast cancer." (PMID 30682127, 2019). "Surprisingly, AKT1 knockdown in prostate cancer cells resulted in a decreased β-catenin level, whereas the pro-metastatic effect of AKT1 in breast cancer was associated with a nuclear accumulation of β-catenin." (PMID 31752925, 2019). "We conducted a phase II trial with an allosteric AKT inhibitor MK-2206 in patients with advanced breast cancer who had tumors with PIK3CA/AKT1 mutations and/or PTEN loss/mutation." (PMID 31277699, 2019). "In conclusion, MK-2206 monotherapy had limited clinical activity in advanced breast cancer patients selected for PIK3CA/AKT1 or PTEN mutations or PTEN loss." (PMID 31277699, 2019). "An own analysis of the Cosmic database revealed that AKT1 somatic mutations occur often and are one of the Top 20 mutated genes in breast cancer with a frequency of about 2.9%." (PMID 31752925, 2019). "Accordingly, AKT1 is mutated and AKT2 is amplified in some cases of breast cancer and AKT isoforms are associated with overall survival and therapy response in an isoform-specific manner." (PMID 31752925, 2019). "In our study, the best response was observed in an AKT1 wild-type breast cancer patient who had an upstream PIK3CA mutation, which is in line with the finding of coincident PI3KCA mutations and improved PFS from another study." (PMID 31835495, 2019). "Impressively, knock down of AKT1 in another mouse model causes an increased vascular density of the mammary tumor." (PMID 31752925, 2019). "This generates a BRCA1 deficient-like phenotype in breast cancer, whereupon AKT1 is necessary for the BRCA1-associated breast cancer cell proliferation." (PMID 31752925, 2019). "A tissue-microarray of invasive breast cancer samples also revealed a positive association of AKT1 expression with ER and HER2 status." (PMID 31752925, 2019). "The AKT1 mutation increases proliferation and tumor growth of breast cancer cells to an intermediate extent between wild type and PIK3CA mutated cells." (PMID 31752925, 2019). "MK-2206 monotherapy had limited clinical activity in advanced breast cancer patients selected for PIK3CA/AKT1 or PTEN mutations or PTEN loss." (PMID 31277699, 2019). "IDH codon 132 variants are seen in various cancers, and AKT1 E17K is commonly observed in breast cancer." (PMID 30709382, 2019). "By reconstructing a disease–gene network, we observed that breast cancers have the largest number of associated PTMs and AKT1 has the largest number of PTMs connected to diseases." (PMID 30244175, 2018).
breast cancer (continued). "The E17K mutation of the AKT1 gene is considered a potential diagnostic biomarker for breast cancer, which led us to search for this mutation in our study." (PMID 30227836, 2018). "Gene expression datasets obtained from breast cancer cell lines and clinical samples revealed a strong association between high akt1 expression, low expression of mesenchymal markers and better patient survival." (PMID 29506489, 2018). "Lastly, we discovered AKT1 E17K, a variant linked to many cancer types, including breast cancer, at the somatic level." (PMID 28569218, 2017). "Hypo-methylation and decreased expression of AKT1 were observed significantly associated with breast cancer in this study." (PMID 28301567, 2017). "Hypo-methylation and suppressed expression of AKT1 was observed to be associated with breast cancer in our cohort." (PMID 28301567, 2017). "Patients with breast cancers bearing AKT1E17K mutations exhibit worse outcomes compared with patients with tumours expressing wild-type AKT1." (PMID 28082369, 2017). "Comparison of AKT1 mutation detection by castPCRTM, MALDI-TOF MS and BEAMing in 6 AKT1 E17K mutation positive breast cancer samples." (PMID 28472036, 2017). "In summary, AKT1 promoter mutation and methylation alternation were observed commonly in our cohort of Chinese breast cancer patients." (PMID 28301567, 2017). "Our results suggest a specific role of Akt1 activation in breast cancer brain metastases due to a loss of PTEN." (PMID 28008153, 2017). "Upon successful validation at partner CROs (data not reported), the castPCRTM assay is currently one of the methods accepted for prospective and retrospective AKT1 E17K mutation testing of ER+ breast cancer samples for clinical trial NCT01226316." (PMID 28472036, 2017). "In the present study, we analyzed the AKT1 promoter mutations with next generation sequencing in breast tumor and matched normal tissues from 95 unselected Chinese breast cancer patients." (PMID 28301567, 2017). "Despite its low prevalence, AKT1 E17K has been reported to be an oncogenic driver mutation in breast cancer and other solid cancers." (PMID 28472036, 2017). "This assay enables contemporary identification of the AKT1 E17K mutation in advanced breast cancer patients using a plasma sample." (PMID 28472036, 2017). "In the mutation analysis, we sequenced 1000 bp promoter region of AKT1 from 95 pairs of Chinese breast cancer tissues." (PMID 28301567, 2017). "Since the E17K mutation of AKT1 was firstly identified as a potential biomarker in breast cancer, the coding region of AKT1 has become the hotspot of mutation detection." (PMID 28301567, 2017). "Epidemiologic studies suggested that mutations of the PI3K/PTEN/AKT pathway genes are associated with cancer risk, yet no data are available for PTEN rs701848, PIK3CA rs2699887, and AKT1 rs2494752 polymorphism and breast cancer(BC) risk." (PMID 28423632, 2017). "The single hotspot mutation AKT1 [G49A:E17K] has been described in several cancers, with the highest incidence observed in breast cancer." (PMID 27515171, 2016). "Integrative genomic studies have indicated that the AKT1(E17K) mutation in breast cancer is mutually exclusive with HER2." (PMID 27004402, 2016). "One such genetic lesion is the somatic AKT1(E17K) mutation, which has been identified in 4-8% of breast cancer patients." (PMID 27004402, 2016). "Other gene aberrations such as overexpression of proto-oncogene, HER2, in breast cancer, loss of function E17K mutation of AKT1 and amplification of AKT2 in pancreatic cancer that disrupt usual signaling along this pathway have been reported." (PMID 27826244, 2016). "In the mammary tumor mouse model MTB-IGF-IR loss of Akt1 or Akt2 delays mammary tumor onset and suppresses growth." (PMID 27533079, 2016).
breast cancer (continued). "In the context of breast cancer, the AKT1(E17K) somatic mutation was first identified in breast cancer but is also found in lung, bladder, endometrial, urothelial and prostate cancers." (PMID 27004402, 2016). "The single hotspot mutation in the pleckstrin homology domain of the AKT1 gene [G49A:E17K] has been described in human breast, colon, and ovarian cancers, with the highest incidence observed in breast cancer." (PMID 27515171, 2016). "They confirmed the presence of mutations in driver genes previously implicated in breast cancer development, such as AKT1, BRCA1, CDH1 and GATA3." (PMID 26561834, 2015). "Inhibition of Akt1/Foxo3a/p21/p27 was observed in breast cancer cells with Flot-1 knockdown, which was associated with an arrest of proliferation and tumorigenicity." (PMID 26206082, 2015). "In breast cancer, aberrant AKT1 activation has been reported to be associated with promoter hypermethylation." (PMID 26472088, 2015). "In breast cancer, for example, the hotspot AKT1 E17K mutation occurs in only about 3% of primary breast cancers; however, that gene is an important part of the PI3-kinase-AKT-mTOR pathway, which is frequently mutated in breast cancer." (PMID 26556852, 2015). "Using human cell lines and genetically engineered mice that are deficient in AKT1, it has been demonstrated that signaling through this serine-threonine kinase is critical for the initiation and progression of breast cancer." (PMID 24628780, 2014). "We identified four new AKT1 transcript variants in human breast cancer cells that are orthologous to the murine Akt1m and that encode the full-length kinase." (PMID 24628780, 2014). "Although loss of Akt1 or Akt2 significantly inhibited mammary tumor onset and growth rates these effects were very modest." (PMID 23919516, 2013). "Although loss of Akt1 or Akt2 significantly inhibited mammary tumor onset and growth rates the effects were less dramatic than anticipated." (PMID 23919516, 2013). "We and other teams have found PIK3CA mutations in 10 to 40% of breast cancer cases and AKT1 mutations in less than 10% of cases." (PMID 24229379, 2013). "Recent large-scale breast cancer sequencing studies have identified other somatic sequence variants in the PH domain of AKT1." (PMID 23237847, 2013). "Altogether, we observed PIK3CA and/or PIK3R1 and/or AKT1 mutations in 174/454 (38.3%) breast cancer tumors." (PMID 24229379, 2013). "We chose for study six AKT1 variants reported in recent breast cancer sequencing studies: D32Y, K39N, P42T, L52R, C77F, and Q79K." (PMID 23237847, 2013). "Nuclear expression of FOXO3A in breast cancer is associated with anti-apoptotic signaling via Akt1, an aggressive phenotype and poor survival." (PMID 23696831, 2013). "PIK3CA, PIK3R1 and AKT1 mutations were mutually exclusive and were observed in a total of 175 breast cancer tumors." (PMID 24229379, 2013). "We expressed all of these variants, as well as wild type human Akt1 and the E17K mutant, in a novel derivative of the human breast cancer cell line MCF-7 created in our laboratory." (PMID 23237847, 2013). "This AKT1 E17K somatic mutation was detected in about 5% of breast cancers and 3% of both thyroid and urinary cancers (adapted from the COSMIC database)." (PMID 22666248, 2012). "An activating mutation of Akt1 situated in the pleckstrin homology domain (E17K) was identified in breast cancer and occurs early in the development of the disease." (PMID 22295219, 2011). "For instance, the phenodiv gene AKT1 is associated with divergent phenotypes including schizophrenia, colorectal cancer, ovarian cancer and breast cancer." (PMID 20525321, 2010).